FOXD1 (forkhead box D1)
Description:
Transcription factor involved in regulation of gene expression in a variety of processes, including formation of positional identity in the developing retina, regionalization of the optic chiasm, morphogenesis of the kidney, and neuralization of ectodermal cells (By similarity). Involved in transcriptional activation of PGF and C3 genes.
Synonyms: FREAC-4; FKHL8; FREAC4
Tractability: No criterion of Open Targets' tractability assessment is met for any kind of drug.
Gene: Protein-coding gene on chromosome 5 (73,444,827 to 73,448,777, reverse strand). Ensembl gene ENSG00000251493.
Subcellular location: Nucleus
Gene Ontology:
Molecular function: DNA binding; DNA binding, bending; sequence-specific DNA binding; DNA-binding transcription factor activity; DNA-binding transcription factor activity, RNA polymerase II-specific; RNA polymerase II cis-regulatory region sequence-specific DNA binding; DNA-binding transcription activator activity, RNA polymerase II-specific
Biological process: anatomical structure morphogenesis; cell differentiation; dichotomous subdivision of terminal units involved in ureteric bud branching; metanephric capsule development; metanephric capsule specification; negative regulation of DNA-templated transcription; positive regulation of BMP signaling pathway; positive regulation of gene expression; positive regulation of kidney development; regulation of transcription by RNA polymerase II; canonical Wnt signaling pathway; luteinizing hormone secretion; metanephric nephron development; nephrogenic mesenchyme development; pattern specification involved in metanephros development; positive regulation of transcription by RNA polymerase II; regulation of DNA-templated transcription
Cellular component: chromatin; nucleus
Genetic constraint (gnomAD): Loss-of-function variants: 3 observed, 1.93 expected, observed/expected ratio (o/e) 1.56, 90% interval 0.58 to 1.93. That is too few expected variants to judge how well the gene tolerates losing a copy. Missense variants: 581 observed, 495.32 expected, observed/expected ratio (o/e) 1.17, 90% interval 1.1 to 1.26. Synonymous variants: 353 observed, 254.54 expected, observed/expected ratio (o/e) 1.39, 90% interval 1.27 to 1.51.
Homologues: Orthologues: macaque FOXD1 (98% identical), pig FOXD1 (94% identical), chimpanzee FOXD1 (83% identical), mouse Foxd1 (81% identical), rat Foxd1 (81% identical), dog FOXD1 (63% identical), zebrafish foxd2 (37% identical). Paralogues in human: FOXD2 (49% identical), FOXD3 (45% identical), FOXD4L1 (31% identical), FOXD4 (30% identical), FOXD4L3 (30% identical), FOXD4L5 (30% identical), FOXD4L6 (30% identical), FOXD4L4 (29% identical), FOXE3 (24% identical), FOXC1 (23% identical), FOXC2 (22% identical), FOXB1 (22% identical), and 29 more.
Diseases named in the same sentence as FOXD1 in open-access papers:
FOXD1 is named in the same sentence as 101 diseases in open-access papers, as found by Europe PMC text mining. Sharing a sentence is not in itself a finding about the gene and the disease. The quoted sentences say what the papers report.
colorectal cancer (24 papers, 2019 to 2025). A primary or metastatic malignant neoplasm that affects the colon or rectum. "Moreover, accumulating evidence has demonstrated that FOXD1 is implicated in the carcinogenesis, including lung cancer, colorectal cancer, ovarian cancer, breast cancer, nasopharyngeal carcinoma, gastric cancer, and prostate cancer." (PMID 34269372, 2021). "For instance, elevated FOXD1 expression is obviously associated with lymph nodes metastasis, tumor size and advanced stages in non-small cell lung cancer, nasopharyngeal carcinoma and colorectal cancer." (PMID 34772357, 2021). "For example, higher FOXD1 expression was obviously related with lymph node metastasis, tumor size and advanced stage, in colorectal cancers and nasopharyngeal, non-small cell lung cancer." (PMID 38827805, 2024). "It is of note that FOXD1 is aberrantly overexpressed in colorectal cancer, and it promotes the progression of cancer through the activation of the ERK1/2 signaling pathway." (PMID 38684876, 2024). "In prostate cancer, cervical cancer, and colorectal cancer, FOXD1 is markedly up-regulated and indicates a poor prognosis of the patients; functionally, FOXD1 can promote tumor growth and metastasis." (PMID 34937497, 2022). "CXCL5 induces tumor angiogenesis in colorectal cancer by enhancing FOXD1 expression mediated by the AKT/NF-κB pathway." (PMID 35936390, 2022). "In colorectal cancer, the up-regulated expression of FOXD1 can promote tumor progression by activating the ERK1/2 pathway." (PMID 34937497, 2022). "The results obtained from breast cancer, lung cancer, nasopharyngeal carcinoma, colorectal cancer and prostate cancer are evident, but, the function of FOXD1 in ovarian cancer remain controversial." (PMID 34269372, 2021). "FOXD1 was reported to be overexpressed in colorectal cancer tissues, and expression levels correlated with tumor size, differentiation, tumor node and metastasis (TNM) stage, lymph node metastasis, and poor prognosis." (PMID 33403027, 2021). "In colorectal cancer patients, FOXD1 expression was up-regulalted and correlated with more invasive phenotype, such as lymphatic metastasis and TNM stage." (PMID 34269372, 2021). "CXCL5 as a tumor angiogenic factor promoted the expression of FOXD1 by activating the AKT/NF-κB pathway in colorectal cancer." (PMID 34987577, 2021). "In colorectal cancer, upregulated FOXD1 drives VEGF-A-dependent angiogenesis via CXCR2." (PMID 40999468, 2025). "FOXD1 promotes colorectal cancer cell stemness and enhances chemotherapy resistance." (PMID 41214670, 2025). "FOXD1 could be able to promote cell proliferation and inhibit apoptosis by regulating polo-like kinase 2 in colorectal cancer." (PMID 40173324, 2025). "By regulating histone H3 FOXD1 controls the cell cycle in ccRCC cells of colorectal cancer (CRC)." (PMID 38827805, 2024). "In addition, CXCL5 is positively correlated with the micro-vessel marker CD31, and it activates the AKT/NF-kB/FOXD1/VEGF-A pathway to enhance its tube formation ability in a CXCR2-dependent manner in colorectal cancer." (PMID 36980564, 2023). "Moreover, FOXD1 promoted cell proliferation, migration and invasion in colorectal cancer cells by regulating the phosphorylation of ERK 1/2 pathway." (PMID 35607308, 2022). "FOXD1 promoted the progression of colorectal cancer through ERK 1/2 pathway." (PMID 35395711, 2022). "Recent studies showed that overexpression of FOXD1 were associated with poor OS in colorectal cancer 17, non-small cell lung cancer 18, and breast cancer." (PMID 33403027, 2021). "FOXD1 was also recognized as a cancer‐promoter in various human malignancies, such as melanoma, lung cancer, glioma, colorectal cancer, and breast cancer." (PMID 32460412, 2021). "In addition, high FOXD1 expression in colorectal cancer is reported to predict poor survival of patients, FOXD1 promotes progression of colorectal cancer by activating ERK 1/2 pathway." (PMID 34028536, 2021).
colorectal cancer (continued). "In addition, using both FOXD1 and Plk2 may as a novel biomarker can better predict poor prognosis in colorectal cancer." (PMID 38827805, 2024). "It was reported that CXCL5 could induce angiogenesis of colorectal cancer via upregulating FOXD1." (PMID 35504887, 2022). "It orchestrates the modulation of FOXD1 expression through the activation of the AKT/NF-κB pathway, thereby fostering angiogenesis in colorectal cancer." (PMID 38343536, 2024). "FOXD1 upregulates vascular endothelial growth factor A (VEGFA), which accelerates tumor angiogenesis in colorectal cancer." (PMID 37563111, 2023). "Regarding regulatory role of CXCL5 in tumors, an existing study demonstrated that in colorectal cancer, CXCL5 fosters FOXD1 expression mediated through the AKT/NF-κB pathway to induce angiogenesis." (PMID 35936390, 2022). "It was reported that high expression of FOXD1 was correlated with pathological differentiation in colorectal carcinoma; however, there was no statistical relationship between histological grade and FOXD1 expression in our study about HNSCC." (PMID 36983712, 2023).
breast cancer (23 papers, 2018 to 2025). A primary or metastatic malignant neoplasm involving the breast. "For example, FOXD1 upregulation is associated with poor outcome in patients with basal-like breast cancer, and FOXD1 maintains tumor-promoting enhancer-gene programs." (PMID 41214670, 2025). "We then performed survival analysis to identify genes associated with poor prognosis in basal-like breast cancer, finding that FOXD1 was associated with poor prognosis in basal-like breast cancer but not in other subtypes." (PMID 37234983, 2023). "In basal-like breast cancer, FOXD1 could regulate enhancer gene programs associated with tumor progression and inhibition of FOXD1 could reduce metastasis by inactivating EMT-associated enhancers." (PMID 39494294, 2024). "Accordingly, inhibiting FOXD1 could potentially reduce breast cancer metastasis by inactivating the enhancers associated with EMT." (PMID 37234983, 2023). "However, the present study revealed that FOXD1, a transcription factor that functions in both normal development and malignancy, is associated with poor prognosis in basal-like breast cancer." (PMID 37234983, 2023). "In breast cancer (BC), the FOXD1-dependent RalA-ANXA2-Src complex promotes CTC formation in breast cancer." (PMID 38827805, 2024). "Collectively, our findings suggest that FOXD1 plays a critical role in establishing an aggressive phenotype in a basal-like breast cancer subset by maintaining tumor-promoting epigenetic features and gene expression patterns." (PMID 37234983, 2023). "The expression of FOXD1 is upregulated in primary breast cancer and promotes tumor proliferation and chemoresistance in the MDA-MB-231 (basal-like) and MCF7 (luminal) cell lines." (PMID 37234983, 2023). "Of the 43 prognosis-related genes identified, we focused on FOXD1, a TF involved in breast cancer proliferation and drug resistance." (PMID 37234983, 2023). "Recently, it has been proven that FOXD1 is significantly elevated in breast cancer cells and tissues, and it promotes migration and metastasis of BC cells by upregulating RalA via directly bound to RalA promotor." (PMID 37906341, 2023). "Transcriptomic analysis of the MIND models again identified high expression of ERBB2 and Ki67 as risk factors, as well as additional factors such as S100A8/A9 and FOXD1, which are described to drive breast cancer proliferation." (PMID 37116492, 2023). "The present study and other studies suggest that targeting FOXD1 is an attractive therapeutic approach for basal-like breast cancer." (PMID 37234983, 2023). "The function of FOXD1 involved in cancer evolution has been revealed in nasopharyngeal carcinoma, non‐small cell lung cancer and breast cancer." (PMID 35579380, 2022). "FOXD1 functions as an oncogene in lung, breast, and brain cancers and is upregulated to promote breast cancer cell proliferation and chemoresistance by inducing G1 to S transition." (PMID 33688372, 2021). "Abnormal FOXD1 expression is involved in the progression of tumors including breast cancer, colorectal cancer, melanoma, glioma, osteosarcoma, renal cell carcinoma, ovarian carcinoma, medulloblastoma, and lung cancer." (PMID 31795213, 2019). "FOXD1 might also be related to chemotherapeutic drug resistance for patients with breast cancer by targeting p27 expression and then inducing G1 to S phase transition in the cell cycle." (PMID 36983712, 2023). "Therefore, further research is warranted to develop specific FOXD1 inhibitors and determine the precise role of FOXD1 in cancer using breast cancer preclinical models." (PMID 37234983, 2023). "In this study, we analyzed publicly available expression data from clinical specimens, finding that elevated expression of FOXD1 is associated with poor outcomes in basal-like breast cancer but not in other subtypes." (PMID 37234983, 2023). "FOXD1 is upregulated in prostate cancer, lung cancer and breast cancer." (PMID 36983712, 2023).
breast cancer (continued). "In breast cancer, FOXD1 could induce G1 to S phase transition, thus promoting cell proliferation and chemoresistance." (PMID 35607308, 2022). "In addition, PXDNL and FOXD1 were reportedly involved in breast cancer pathogenesis and were significant in predicting prognosis." (PMID 35619902, 2022). "FOXD1 was found to be significantly related to the prognosis of basal-like breast cancer." (PMID 35619902, 2022). "In contrast, in breast cancer, FOXD1 promotes drug resistance by downregulating P27." (PMID 31795213, 2019). "In addition our study further confirmed that high levels of FOXD1, ITGA6 and SERPINE1 were associated with HER2-overexpressing breast cancer cells resistant to trastuzumab and they were regulated by acetylation of H3K27 and H3K18." (PMID 30914750, 2019). "For example, FOXD1 enhances the aerobic glycolysis process by increasing HK2, LDHA, and GLUT1 expression in breast cancer cells." (PMID 41214670, 2025). "FOXD1-4 are crucial members of the FOX family and promotes cancer cell proliferation in nasopharyngeal carcinoma, non-small cell lung cancer, and breast cancer." (PMID 39494294, 2024). "Therefore, FOXD1 may be a lineage-specific tumor-promoting TF in basal-like breast cancer." (PMID 37234983, 2023). "Then, our RNA sequencing and chromatin immunoprecipitation sequencing experiments using the basal-like breast cancer cell lines BT549 and Hs578T with FOXD1 knockdown revealed that FOXD1 regulates enhancer–gene programs related to tumor progression." (PMID 37234983, 2023). "In similar, MTX, Etoposide, Fulvestrant, and Resveratrol could suppress the expression of FOXD1, FOXA1, FOXM1, and FOXP1, respectively, which exhibited oncogenic potential in LGG, PRCA/breast cancer, LUAD/LUSC, and PAAD." (PMID 36292640, 2022).
glioma (15 papers, 2019 to 2025). A benign or malignant brain and spinal cord tumor that arises from glial cells (astrocytes, oligodendrocytes, ependymal cells). "FOXD1 has also been shown to be associated with osteoarthritis, gastric intestinal metaplasia, glioma, cellular differentiation and other deleterious effects." (PMID 36057597, 2022). "In gliomas through controlling aerobic glycolysis, FOXD1 subsequently increases GLUT1 expression and finally promotes PC cell proliferation, metastasis, invasion, and cell proliferation." (PMID 38827805, 2024). "The combined inhibition of UBA2, RALY, and FOXD1 significantly impeded glioma cell migration, invasion, and VM compared with the control group." (PMID 37906341, 2023). "Glioma cells treated with FOXD1 inhibition showed decreased VM, whereas those overexpressing FOXD1 showed enhanced VM." (PMID 37906341, 2023). "In glioma, FOXD1 has been found to activate signaling pathways that contribute to the tumorigenicity of mesenchymal glioma stem cells by activating ALDH1A3 transcription." (PMID 37234983, 2023). "Overexpression of DKK1 rescued the suppression of migration, invasion, and VM induced by FOXD1 knockdown in glioma cells." (PMID 37906341, 2023). "Western blot showed that the transfection of si-SNHG18#1 inhibited the expression of FOXD1 protein in glioma cells, and co-transfection of miR-338-5p inhibitors rescued it." (PMID 34937497, 2022). "In summary, this work demonstrates that knocking down SNHG18 suppresses the malignant phenotypes of glioma cells via modulating miR-338-5p and FOXD1." (PMID 34937497, 2022). "Our data suggest that SNHG18/miR-338-5p/FOXD1 axis is a vital downstream mechanism by which E2F1 participates in regulating glioma progression." (PMID 34937497, 2022). "Mechanistically, it is revealed that E2F1 is a regulator for SNHG18/miR-338-5p/FOXD1 axis in glioma." (PMID 34937497, 2022). "Forkhead Box D1 (FOXD1) regulates the transcriptional activity of ALDH1A3 in glioma stem cells (GSCs) of MES subtype." (PMID 32680476, 2020). "FOXD1 stabilization promotes vasculogenic mimicry in glioma cells by activating DKK1 transcription." (PMID 40999468, 2025). "Indeed, previous studies in cancers have shown that SNHG18 promotes FOXD1 expression by decoying miR-338-5p,75 suppresses nucleocytoplasmic transport of α-enolase, and inhibits semaphorin 5A31 in glioma cells." (PMID 38498586, 2024). "In addition, recent research has indicated that the expression of FOXD1 is increased in glioma, while its inhibition decreases cell viability and migration and promotes cell senescence in the human glioblastoma cell line." (PMID 37906341, 2023). "Inhibition of RALY hindered migration, invasion, and VM in glioma cells via FOXD1 destabilization." (PMID 37906341, 2023). "Moreover, it shows increased expression of FOXD1 in mesenchymal glioma stem cells and contributes to glial neoplasms by upregulating the expression of the aldehyde dehydrogenase isoform ALDH1A3 via directly activating its promoter." (PMID 37906341, 2023). "FOXD1 has been reported to act as a malignant factor in gastric intestinal metaplasia and glioma." (PMID 37563111, 2023). "The results confirmed that FOXD1 transcriptionally activated DKK1 expression in glioma cells." (PMID 37906341, 2023). "However, further investigation is required to explore the role of FOXD1 in the regulation of the vasculogenic mimicry in glioma cells." (PMID 37906341, 2023). "In glioma, FOXD1 expression is also up-regulated and its high expression indicates a poor prognosis; knocking down FOXD1 inhibits glioma cell proliferation and migration; FOXD1 down-regulates p27 expression to induce G1/S transition and facilitate cell cycle progression." (PMID 34937497, 2022). "Besides, the FOXD1 expression in the bran lower-grade glioma (LGG) group was higher than that in the control group." (PMID 36292640, 2022). "In conclusion, SNHG18 accelerates glioma progression via regulating the miR-338-5p/FOXD1 axis." (PMID 34937497, 2022).